CSNK1G1 (casein kinase 1 gamma 1)
Description:
Serine/threonine-protein kinase. Casein kinases are operationally defined by their preferential utilization of acidic proteins such as caseins as substrates. It can phosphorylate a large number of proteins. Participates in Wnt signaling. Regulates fast synaptic transmission mediated by glutamate (By similarity). Phosphorylates CLSPN.
Synonyms: CK1gamma1
Tractability: Small molecule: a structure with a bound ligand is known; a high-quality ligand is known; it has a binding pocket of medium quality; it belongs to a druggable protein family. Antibody: its Gene Ontology location is reachable by antibodies, with medium confidence. PROTAC: ubiquitination databases record sites on it; its protein half-life has been measured; a small molecule that binds it is known.
Target class: CK1 protein kinase group; Enzyme; CK1 protein kinase CK1 family; Protein Kinase; Kinase
Gene: Protein-coding gene on chromosome 15 (64,165,525 to 64,356,554, reverse strand). Ensembl gene ENSG00000169118.
Subcellular location: Cytoplasm
Subcellular location (Human Protein Atlas): Cytosol
Gene Ontology:
Molecular function: protein binding; protein serine/threonine kinase activity; ATP binding; protein kinase activity; protein serine kinase activity
Biological process: endocytosis; positive regulation of canonical Wnt signaling pathway
Cellular component: cytosol; plasma membrane; cytoplasm
Genetic constraint (gnomAD): Loss-of-function variants: 14 observed, 33.61 expected, observed/expected ratio (o/e) 0.42, 90% interval 0.27 to 0.65. The upper end of that interval is the gene's LOEUF score, 0.65, which puts it in group 2 of 6, group 1 being the genes least tolerant of losing a copy. Missense variants: 286 observed, 415.81 expected, observed/expected ratio (o/e) 0.69, 90% interval 0.62 to 0.76. Synonymous variants: 141 observed, 148.47 expected, observed/expected ratio (o/e) 0.95, 90% interval 0.83 to 1.09.
Homologues: Orthologues: pig CSNK1G1 (99% identical), mouse Csnk1g1 (98% identical), rat Csnk1g1 (97% identical), chimpanzee CSNK1G1 (96% identical), macaque CSNK1G1 (96% identical), dog CSNK1G1 (96% identical), rabbit CSNK1G1 (95% identical), guinea pig CSNK1G1 (94% identical), tropical clawed frog csnk1g1 (89% identical), zebrafish csnk1g1 (89% identical), Drosophila melanogaster CG9962 (27% identical), Caenorhabditis elegans C28A5.6 (23% identical), and 63 more. Paralogues in human: CSNK1G3 (81% identical), CSNK1G2 (79% identical), CSNK1D (45% identical), CSNK1E (45% identical), CSNK1A1 (40% identical), CSNK1A1L (38% identical), TTBK1 (31% identical), TTBK2 (29% identical), VRK1 (25% identical), VRK2 (22% identical), CDC7 (19% identical), VRK3 (17% identical).
Diseases named in the same sentence as CSNK1G1 in open-access papers:
CSNK1G1 is named in the same sentence as 17 diseases in open-access papers, as found by Europe PMC text mining. Sharing a sentence is not in itself a finding about the gene and the disease. The quoted sentences say what the papers report.
autism spectrum disorder (3 papers, 2022 to 2023). A spectrum of developmental disorders that includes autism, and Asperger syndrome. "Nina B. Gold's case report showed that CSNK1G1 associated syndromic developmental delay which all individuals have delayed growth, and possibly associated with autism spectrum disorder, facial features and seizure." (PMID 37454083, 2023). "Intriguingly, a recent study reported that de novo variants in CSNK1G1 were associated with syndromic developmental delay and autism spectrum disorder in humans." (PMID 35800758, 2022). "TRIP4 gene has been identified as a candidate gene for Alzheimer’s disease susceptibility, and the CSNK1G1 gene may be a cause of syndromic developmental delay and autism spectrum disorder." (PMID 36658485, 2023).
colorectal cancer (2 papers, 2022). A primary or metastatic malignant neoplasm that affects the colon or rectum. "The expression of circ‐CSNK1G1 was also aberrantly strengthened in colorectal cancer tissues." (PMID 35023214, 2022). "Interestingly, the expression of circ-CSNK1G1 was also shown to be increased in colorectal cancer." (PMID 36109751, 2022).
hepatocellular carcinoma (2 papers, 2022). A malignant tumor that arises from hepatocytes. "For example, circ‐CSNK1G1 level was increased in hepatocellular carcinoma (HCC) tumor tissues, and circ‐CSNK1G1 knockdown repressed tumor growth in animal model." (PMID 35023214, 2022). "Besides, circ-CSNK1G1 was also demonstrated to be highly expressed in hepatocellular carcinoma (HCC) tissues, and circ-CSNK1G1 knockdown inhibited HCC cell proliferation and colony formation, as well as tumor growth in vivo." (PMID 36109751, 2022).
breast carcinoma (1 paper, 2022). "Circ-CSNK1G1 was firstly identified to be overexpressed in breast cancer tissues in a circRNA profile." (PMID 36109751, 2022). "The similar expression pattern of circ-CSNK1G1 in breast cancer was also revealed in another microarray data, highlighting the dysregulation of circ-CSNK1G1 in breast cancer." (PMID 36109751, 2022).
breast tumor (1 paper, 2022). "In short, circ-CSNK1G1 downregulation blocked breast tumor growth in vivo." (PMID 36109751, 2022).
Epileptic encephalopathy (1 paper, 2014). A condition in which epileptiform abnormalities are believed to contribute to the progressive disturbance in cerebral function. "Using a targeted resequencing approach, we screened KCNT1, PIGQ, CBL and CSNK1G1 in a large cohort of epileptic encephalopathy cases from Australia." (PMID 24463883, 2014).
papillary thyroid cancer (1 paper, 2022). "Only a circRNA microarray profile presented that circ‐CSNK1G1 was one of the circRNAs that were significantly upregulated in papillary thyroid cancer tissues." (PMID 35023214, 2022). "It was shown to be highly regulated in papillary thyroid cancer tumor tissues compared with normal tissues through microarray analysis by the public GEO database (accession: GSE93522), hinting that circ‐CSNK1G1 was involved in thyroid cancer development." (PMID 35023214, 2022).
thyroid cancer (1 paper, 2022). "The evidence supported that cancer aggressive development might be associated with increased circ‐CSNK1G1 expression, whereas the role of circ‐CSNK1G1 in thyroid cancer was poorly investigated." (PMID 35023214, 2022). "Circ‐CSNK1G1 downregulation restrained the proliferation, colony formation, survival, and invasion of thyroid cancer cells in vitro and tumor development in vivo." (PMID 35023214, 2022). "Our current data mainly found that circ‐CSNK1G1 was overexpressed in tumor tissues of thyroid cancer relative to normal tissues." (PMID 35023214, 2022). "Circ‐CSNK1G1 promoted the malignant development of thyroid cancer partially by activating MAPK1 via competitively targeting miR‐149‐5p." (PMID 35023214, 2022). "This work intended to determine the role of circ‐CSNK1G1 in thyroid cancer and provide a mechanism to explain its function." (PMID 35023214, 2022). "The purpose of this work was to explore the role of circRNA casein kinase 1 gamma 1 (circ‐CSNK1G1) in thyroid cancer." (PMID 35023214, 2022). "The data from GSE3522 dataset (a circRNA expression profile) showed that has_circRNA_101555 (circ‐CSNK1G1) was one of the forcefully expressed circRNAs in thyroid cancer tissues compared with normal tissues." (PMID 35023214, 2022). "These present findings deepened the insights into the realizing of the role of circ‐CSNK1G1 in thyroid cancer." (PMID 35023214, 2022). "Then, we found that circ‐CSNK1G1 expression was strikingly higher in tumor tissues of thyroid cancer than that in matched normal tissues." (PMID 35023214, 2022). "Taken together, this study was the first study to exploit the detailed functions of circ‐CSNK1G1 in thyroid cancer." (PMID 35023214, 2022). "Nonetheless, the detailed functions of circ‐CSNK1G1 in thyroid cancer were still unclear." (PMID 35023214, 2022). "The present work discovered the upregulation of circ‐CSNK1G1 in tumor tissues of thyroid cancer." (PMID 35023214, 2022). "The downregulation of circ‐CSNK1G1 inhibited cancer cell colony formation, proliferation, survival, and invasion, which supported that circ‐CSNK1G1 was a carcinogenic driver at least in thyroid cancer." (PMID 35023214, 2022). "Our study provides a basis for characterizing the role of circ‐CSNK1G1 in thyroid cancer." (PMID 35023214, 2022). "Our current work was the first to investigate the detailed role of circ‐CSNK1G1 in thyroid cancer." (PMID 35023214, 2022). "It was unknown whether circ‐CSNK1G1 functioned by targeting miR‐149‐5p in thyroid cancer." (PMID 35023214, 2022). "We thus explored the detailed role of circ‐CSNK1G1 in thyroid cancer and found that circ‐CSNK1G1 downregulation suppressed the proliferation, survival, and invasion of cancer cells and tumor growth in vivo in thyroid cancer, which was consistent with the role of circ‐CSNK1G1 in other cancers." (PMID 35023214, 2022). "Circ‐CSNK1G1 acted as miR‐149‐5p to relieve the inhibition of miR‐149‐5p on MAPK1, thus promoting the malignant development of thyroid cancer." (PMID 35023214, 2022).
triple-negative breast carcinoma (1 paper, 2022). An invasive breast carcinoma which is negative for expression of estrogen receptor (ER), progesterone receptor (PR), and human epidermal growth factor receptor 2 (HER2). "Our study aimed to disclose the role of circ-CSNK1G1 in triple-negative breast cancer (TNBC)." (PMID 36109751, 2022).
cancer (4 papers, 2019 to 2023). A tumor composed of atypical neoplastic, often pleomorphic cells that invade other tissues. "By reviewing the previous studies, we discovered that circ‐CSNK1G1 served as an oncogenic role to facilitate the malignant progression of diverse cancers." (PMID 35023214, 2022). "Circ-CSNK1G1 knockdown suppressed cancer cell proliferation, migration, invasion and glycolysis energy metabolism, promoted cell apoptosis in vitro, and blocked tumor growth in vivo." (PMID 36109751, 2022). "The findings mainly manifested that circ-CSNK1G1 expression was abnormally enhanced in tumor tissues and cancer cells." (PMID 36109751, 2022). "Transwell assay pointed out that circ-CSNK1G1 knockdown suppressed cancer cell malignant migration and invasion." (PMID 36109751, 2022). "In function, circ‐CSNK1G1 knockdown inhibited proliferation, survival, and invasion in cancer cells, and tumor growth in mouse models." (PMID 35023214, 2022). "We mainly found that circ-CSNK1G1 acted as a cancer-driver to promote cell proliferation, migration, invasion and glycolysis energy metabolism in TNBC through the miR-28-5p/LDHA pathway." (PMID 36109751, 2022). "As a result, circ-CSNK1G1 was also highly expressed in tumor tissues (N = 33) compared to paired non-cancer tissues (N = 33)." (PMID 36109751, 2022). "The second network contained 6 of the identified autoantigens (AGO1, CSNK1G1, IFIT5, PHC3, SRP19, and UBE2S) out of the 35 molecules associated with cancer, organismal injury and abnormalities." (PMID 31494269, 2019). "Moreover, mechanism analysis suggested that circ‐CSNK1G1 played carcinogenic effects in this cancer by acting as miR‐149‐5p sponge and relieving the inhibition of miR‐149‐5p on MAPK1." (PMID 35023214, 2022). "Innovatively, our study explored the detailed function of circ-CSNK1G1 and discovered that circ-CSNK1G1 knockdown inhibited cancer cell proliferation, colony formation, migration, invasion and glycolysis energy metabolism in vitro and blocked tumor formation and growth in vivo." (PMID 36109751, 2022). "Besides, circ-CSNK1G1 overexpression markedly promoted cancer cell proliferation, while the proliferation was blocked with the addition of 2-DG, an inhibitor of glycolysis." (PMID 36109751, 2022). "In addition, circ‐CSNK1G1 knockdown‐induced cancer cell apoptosis and cell cycle arrest were largely relieved by miR‐149‐5p inhibition." (PMID 35023214, 2022). "We thus defined that circ-CSNK1G1 was a cancer-driver in TNBC." (PMID 36109751, 2022).
tumor (4 papers, 2017 to 2024). "The most common loss was assigned to CSNK1G1 found in 4 grade G1 and 2 grade G3 tumours." (PMID 28486536, 2017). "To further investigate the role of CSNK1G1 in impacting tumor metastasis, we utilized the constructed SHC1-OE-ISOHAS and Ctrl-OE-ISOHAS cells and treated them with the CSNK1G1 inhibitor." (PMID 38360860, 2024). "The data showed that circ-CSNK1G1 knockdown significantly inhibited tumor volume from day 17 after injection." (PMID 36109751, 2022). "MiR‐149‐5p was a target of circ‐CSNK1G1, and the anti‐tumor effects of circ‐CSNK1G1 knockdown were abolished by miR‐149‐5p downregulation." (PMID 35023214, 2022). "We found that tumor volume in the sh‐circ‐CSNK1G1 group was significantly lower than that in the sh‐NC group at the day 19 post‐injection." (PMID 35023214, 2022). "All data suggested that circ‐CSNK1G1 knockdown inhibited tumor growth and development through miR‐149‐5p‐mediated MAPK1 inhibition." (PMID 35023214, 2022). "The expression of MAPK1 protein was pronouncedly declined in sh‐circ‐CSNK1G1‐administered tumor tissues." (PMID 35023214, 2022). "IHC assay presented that the expression of Ki67, MMP2 and MMP9 was strikingly lower in sh-circ-CSNK1G1-administered tumor tissues relative to sh-NC, suggesting the growth of tumor tissues was suppressed by sh-circ-CSNK1G1." (PMID 36109751, 2022). "Besides, miR-28-5p expression in tumor tissues was negatively correlated with circ-CSNK1G1 expression." (PMID 36109751, 2022). "Tumor formation assay in nude mice was conducted to verify the role of circ-CSNK1G1 in vivo." (PMID 36109751, 2022). "A circRNA expression profile (GEO accession: GSE101123) provided several differently expressed circRNAs in TNBC tissues (N = 8) compared to non-tumor breast tissues (N = 3), and the results from the heat map showed that has_circRNA_101555 (circ-CSNK1G1) was notably upregulated in TNBC tissues." (PMID 36109751, 2022). "Moreover, the expression of circ-CSNK1G1 in sh-circ-CSNK1G1-injected tumor tissues was notably lower than that in sh-NC-injected tumor tissues." (PMID 36109751, 2022). "Besides, miR‐149‐5p expression was negatively correlated with circ‐CSNK1G1 expression in tumor tissues." (PMID 35023214, 2022). "Moreover, IHC analysis presented that the abundance of MAPK1, CyclinD1, and MMP9 was markedly decreased in tumor tissues from the sh‐circ‐CSNK1G1 group." (PMID 35023214, 2022). "Finally, mice with sh-circ-CSNK1G1 injection harbored poor tumor size and tumor weight compared to sh-NC." (PMID 36109751, 2022). "Moreover, the data from qPCR showed that the expression of circ‐CSNK1G1 was decreased, while the expression of miR‐149‐5p was enhanced in sh‐circ‐CSNK1G1‐administered tumor tissues." (PMID 35023214, 2022). "Besides, circ‐CSNK1G1 knockdown inhibited tumor weight, leading to smaller tumor size." (PMID 35023214, 2022).
infection (1 paper, 2022). The state of being infected such as from the introduction of a foreign agent such as serum, vaccine, antigenic substance or organism. "BT-549 cells were infected with sh-circ-CSNK1G1 or sh-NC, and then we found circ-CSNK1G1 expression was notably decreased in BT-549 cells after sh-circ-CSNK1G1 infection." (PMID 36109751, 2022).
neurodevelopmental disorder (1 paper, 2023). A behavioral and cognitive disorder with onset during the developmental period that involves impaired or aberrant development of intellectual, motor, or social functions. "This case report enhanced the candidacy of CSNK1G1 as a cause of a neurodevelopmental disorder." (PMID 37454083, 2023).
CSNK1G1 also shares sentences with these, for which no sentence is quoted: developmental delay (2 papers); Alzheimer disease (1); Cognitive impairment (1); depression (1).